PNLIP (pancreatic lipase)
Diseases named in the same sentence as PNLIP in open-access papers (continued):
Sharing a sentence is not in itself a finding about the gene and the disease.
Obesity (continued). "Orlistat is the only conventional drug used for obesity treatment through the inhibition of pancreatic lipase, but the side effects of the drug have ignited the hunt to develop plant-based lipase-inhibiting drugs for obesity." (PMID 38473839, 2024). "Orlistat is a medication used to treat obesity by inhibiting gastric and pancreatic lipase, preventing dietary triacylglycerol absorption." (PMID 39456515, 2024). "Through comprehensive in vitro investigations, we demonstrated the inhibitory effect of AqLs on pancreatic lipase activity, indicating its potential as a candidate for developing anti-obesity agents." (PMID 39539624, 2024). "Understanding the potential of Cu-GO nanocomposites in mitigating obesity-related processes involved evaluating their anti-obesity activity through the inhibition of pancreatic lipase enzyme." (PMID 38399142, 2024). "In an experimental mice model of obesity, persimmon tannins showed an inhibitory effect on pancreatic lipase, suggesting a reduction in fat absorption via inhibition of pancreatic lipase." (PMID 39767014, 2024). "The anti-diabetic and anti-obesity properties of MO go hand-in-hand since MO combats obesity by inhibiting pancreatic lipase and ghrelin, preventing the accumulation of white adipose tissue and maintaining a healthy plasma lipid profile." (PMID 38496871, 2024). "Collectively, these findings suggest that the bioactive compounds of turmeric, in particular curcumin, can be promising dietary pancreatic lipase inhibitors for the prevention and management of obesity." (PMID 39125445, 2024). "Researchers are increasingly interested in discovering new pancreatic lipase inhibitors as anti-obesity ingredients." (PMID 39125445, 2024). "The top metabolites correlating with anti-obesity activity represented by pancreatic lipase inhibition activity were picked by analyzing Pearson’s correlation coefficients." (PMID 37512578, 2023). "It has been clinically noticed that the pancreatic lipase inhibitor orlistat has a beneficial approved effect on obesity and hyperlipidemia by increasing fat excretion through the feces and by inhibiting pancreatic lipase." (PMID 36604684, 2023). "It was previously demonstrated that fucoxanthin also reduces obesity by altering lipid metabolism, so in this research, a good pancreatic lipase inhibition, obtained for all fractions, especially F3, can be attributed to its presence." (PMID 37107232, 2023). "Related to pharmacotherapy (anti-obesity treatment) is to block pancreatic lipase, a pancreatic enzyme that separates triglycerides into mono acyl glycerol and free fatty acids to ease their absorption." (PMID 36997571, 2023). "The mechanisms exploited by marketed anti-obesity medicines are appetite suppression by increasing norepinephrine, dopamine, and serotonin in the synaptic clefts, pancreatic lipase, and amylase inhibition, and gastric emptying slowing." (PMID 37408757, 2023). "Lignocellulosic biomass-derived PACs’ influence on pancreatic lipase proved in the study, along with PACs’ and the lipophilic extracts’ anti-microbial activity, can be used in complex treatments for obesity and its accompanying microbial infections." (PMID 37623866, 2023). "Ginsenosides Rb1, Rb2, Rc, and Rd were found to significantly inhibit pancreatic lipase activity, which can prevent obesity by increasing fat excretion into feces." (PMID 37188264, 2023). "The α-amylase and pancreatic lipase are digestive enzymes that are effective targets in obesity and type II diabetes treatment." (PMID 37107232, 2023). "Further anti-obesity effects of this compound were depicted by Jung, where dieckol extracted from E. bicyclis ethanol extract had strong inhibitory effects on pancreatic lipase enzyme." (PMID 37103396, 2023). "Phenolic derivatives have been shown to ameliorate obesity via several mechanisms, including the inhibition of pancreatic lipase (Wan‐Loy & Siew‐Moi, 2016)." (PMID 36655073, 2023).
Obesity (continued). "Currently, anti-obesity drugs primarily consist of centrally acting analgesics and pancreatic lipase inhibitors like orlistat and lorcaserin." (PMID 37571229, 2023). "The protein-protein interactions of the upregulated and downregulated genes were mapped to form a network, whereinPNLIP (Pancreatic lipase) and FTO (Fat mass and obesity associated protein) gene clusters were visualized as densely connectedclusters in MCODE." (PMID 37808366, 2023). "Phytochemicals can exert their anti-obesity effects through different mechanisms such as inhibiting digestive enzyme activities (pancreatic lipase and amylase), appetite regulation, and reducing the formation of WAT or increasing WAT browning." (PMID 37408757, 2023). "Pancreatic lipase is a digestive enzyme that breaks down fat and improves triglyceride (TG) absorption; therefore, blocking pancreatic lipase can have an anti-obesity effect." (PMID 37836464, 2023). "Here, IX treatment improved obesity and metabolic disorders through the inhibition of pancreatic lipase activity and intestinal bacteria-mediated action." (PMID 37709134, 2023). "Several surgical procedures, such as biliointestinal bypass or gastric banding, and pharmacological interventions, such as pancreatic lipase inhibitors or Glucagon-Like Peptide 1 agonists, are applied for the management of obesity." (PMID 36768633, 2023). "Orlistat, a gastro–pancreatic lipase inhibitory agent, is now licenced for the treatment of long-term obesity, although it produces gastrointestinal adverse effects such as oily spotting, bloating, faecal urgency, faecal incontinence, and steatorrhoea." (PMID 37754397, 2023). "In vitro inhibition of porcine pancreatic lipase was used to determine the anti-obesity potential of quercetin and the apple extracts." (PMID 37508324, 2023). "As the crucial lipolytic enzyme synthesized and secreted by the pancreas, human pancreatic lipase (hPL) is a predominant anti-obesity target, responsible for the regulation of lipid digestion and absorption in vivo." (PMID 36832040, 2023). "Taken together, strictinin is assumed to be the key ingredient responsible for the empirical anti-obesity effects of Pu’er tea, presumably via the prevention of fat absorption from diets by inhibiting pancreatic lipase activity." (PMID 37175375, 2023). "Orlistat is, at present, the only pancreatic lipase inhibitor approved for the treatment of obesity; however, an array of gastrointestinal adverse effects associated with orlistat limits its tolerability." (PMID 35956860, 2022). "The in vitro enzymatic inhibition results showed that AEEE and all isolates 1–5 possessed antidiabetic and potential anti-obesity activities based on the inhibition of pancreatic lipase, β-glucosidase and α-amylase." (PMID 35161433, 2022). "Obesity is alleviated by the suppression of pancreatic lipase, fatty acid synthesis and fat absorption." (PMID 35495935, 2022). "The pancreatic lipase (PL) is a crucial enzyme involved in triglycerides’ hydrolysis in the gastrointestinal tract, and its inhibition can ameliorate obesity by minimizing lipid absorption." (PMID 35204122, 2022). "In the metabolism of dietary fat, pancreatic lipase plays a major role to promote fat absorption of small intestine, which leads to fat accumulates and obesity." (PMID 36185652, 2022). "The antidiabetic and anti-obesity potential was investigated spectrophotometrically in vitro by the ability to modulate pancreatic lipase and α-glucosidase at different concentrations using orlistat and acarbose as reference drugs." (PMID 36219451, 2022). "For instance, soy peptides prevented obesity by activating a leptin-like signaling pathway, whereas cocoa peptides exhibit anti-obesity potential by inhibiting pancreatic lipase and preventing NCDs development." (PMID 36499253, 2022).
Obesity (continued). "Pancreatic lipase inhibitors, which can make pancreatic lipase lose part of the decomposition ability and thereby reduce the accumulation of fatty acids in the body, are considered as one class of effective anti-obesity agents." (PMID 35684413, 2022). "Inhibition of pancreatic lipase is a clinically validated approach in the treatment of obesity, as it reduces the hydrolysis of fats and decreases their absorption." (PMID 35057523, 2022). "Orlistat is an approved anti-obesity drug with strong pancreatic lipase activity, which can prevent the human body from absorbing about 30% of dietary fat." (PMID 36034931, 2022). "Six major compounds from sea grape (C. racemosa) extract were evaluated using an in silico approach against human pancreatic lipase, a-glucosidase, and a-amylase to predict prospective anti-obesity candidates." (PMID 35911110, 2022). "It was mixed with chloroformate in pyridine to form cetilistat, which is a pancreatic lipase inhibitor for the treatment of obesity." (PMID 36386646, 2022). "At the present time, the only approved anti-obesity drug that acts by inhibiting pancreatic lipase is orlistat, which, however, is known to have multiple gastrointestinal side effects." (PMID 35956860, 2022). "Orlistat, a commonly used drug for obesity treatment, can selectively inhibit pancreatic lipase and prevent 30% of dietary fat absorption." (PMID 35408540, 2022). "One of the strategies for obesity treatment is to inhibit the activity of pancreatic lipase—an enzyme responsible for breaking down the lipids from food in order to make them available to the body." (PMID 35885378, 2022). "Reducing fats and carbohydrates is one dietary treatment option for obesity because it inhibits the enzymatic activity of pancreatic lipase." (PMID 35458674, 2022). "Orlistat remains one of the leading anti-obesity therapeutics on the market, and functions by inhibiting gastric and pancreatic lipase activity within the gastrointestinal (GI) tract." (PMID 36145561, 2022). "The pancreatic lipase inhibitor can effectively inhibit pancreatic lipase activity, impede excessive fat accumulation, and play a role in controlling and treating obesity." (PMID 36185652, 2022). "Anti-obesity strategies focus on suppression of energy intake and stimulation of energy expenditure by regulating lipid metabolism, such as inhibiting pancreatic lipase activity and adipocyte differentiation." (PMID 35495935, 2022). "Orlistat (tetrahydrolipstatin, or its commercial name, Xenical) is the best-known pancreatic lipase inhibitor currently used to treat obesity." (PMID 35897908, 2022). "Reducing dietary fat digestion and absorption by modulating the activity of pancreatic lipase has become a favorable strategy to tackle obesity." (PMID 35956860, 2022). "One of the effective strategies in obesity treatment is the inhibition of PNLIP, which is possible to be achieved by specific phenolic compounds occurring in high abundance in some plants." (PMID 36232503, 2022). "Prunus armeniaca leaves contain phenolic compounds that show several activities, all of them have positive effect on reducing obesity, in particular inhibiting the pancreatic lipase." (PMID 36501129, 2022). "Over 5 weeks of administration in HFD-induced obese mice, three doses of PRF exhibited an equal or even better obesity protective effect than a current anti-obesity drug, orlistat, whose mechanism involves inhibiting pancreatic lipase." (PMID 35215514, 2022). "Pancreatic lipase is a key enzyme for digestion of triacylglycerols, and inhibition of lipase has until now been the most explored strategy for treatment of obesity." (PMID 36235143, 2022). "Controlling appetite and thermogenesis, inhibiting pancreatic lipase activity or adipogenesis, encouraging lipolysis, modifying gut microbiota, and improving obesity-related inflammation are major anti-obesity targets of phytochemicals." (PMID 35899227, 2022).
Obesity (continued). "Pancreatic lipase (PNLIP, EC 3.1.1.3) plays a pivotal role in the digestion of dietary lipids, a metabolic pathway directly related to obesity." (PMID 36232503, 2022). "Alpha amylase and pancreatic lipase inhibition are one therapeutic method to reduce hyperglycaemia and obesity." (PMID 36620201, 2022). "For this pharmacological validation, a panel of enzymes were chosen whereby α-amylase and α-glucosidase are used for DM type 2, AChE and BChE for AD, tyrosinase and elastase for cutaneous manifestations and pancreatic lipase for obesity." (PMID 35335362, 2022). "A member of Penicillium showed potential inhibitory activity on pancreatic lipase, which has been widely recognized as one of the safest drug targets for diet-induced anti-obesity development." (PMID 35783435, 2022). "First, SPE, in which resin glycoside was found as the dominant constituent, was suggested as a potential anti-obesity agent, because 20–70% pancreatic lipase (PL) inhibition was measured with SPE by in vitro turbidity assay and pNPP assay." (PMID 36505243, 2022). "Pancreatic lipase (PL) inhibitor therapy has been validated as an efficacious way for preventing and treating obesity and overweight." (PMID 35284458, 2022). "In terms of anti-obesity properties, there is ongoing evidence that phenolic compounds inhibit PNLIP activity." (PMID 36232503, 2022). "Pancreatic lipase hydrolyzes dietary fat into free fatty acids and monoglycerides, and its inhibitor (orlistat) is widely used as an anti-obesity drug in clinical settings." (PMID 33557332, 2021). "PrALe showed the most effective anti-obesity action via inhibition of pancreatic lipase, cyclooxygenase-1, and antioxidant capacity, especially the oxygen radical absorbance capacity, which was particularly correlated with polyphenolic compounds." (PMID 34942972, 2021). "Nevertheless, its inhibitory effect on pancreatic lipase activity and anti-obesity effect of eggplant have been shown." (PMID 34094022, 2021). "Inhibition of pancreatic lipase activity is one of the most effective methods for the treatment of obesity and obesity-related metabolic disorders, such as atherosclerosis and hyperlipidemia." (PMID 34916951, 2021). "The prospective anti-obesity agent for decreasing fat absorption by inhibiting pancreatic lipase of unripe Diospyros kaki fruits (Diospyros kaki Thunb)." (PMID 34579162, 2021). "With respect to determining anti-obesity potentials, we also examined the inhibitory effects of extracts and fractions on pancreatic lipase activity." (PMID 33557332, 2021). "On account of the inhibition of pancreatic lipase activity being one of the effective ways to prevent obesity, more and more people are paying attention to it." (PMID 34361800, 2021). "The EO of the (AJ) plant showed dose-dependent inhibitory activity against porcine pancreatic lipase, α-amylase, and α-glucosidase, compared with the positive controls, which were the anti-obesity drug orlistat and the antidiabetic medication acarbose." (PMID 34068826, 2021). "Because eggplant has the potential to reduce pancreatic lipase activity, future studies can investigate the anti-obesity effects of eggplant." (PMID 34094022, 2021). "In vitro experiments demonstrated that walnut meal peptides interfered with the micellar solubility of cholesterol and the activity of pancreatic lipase, indicating possible mechanisms for their hypocholesterolemic and anti-obesity effects." (PMID 33922242, 2021). "Ellagic acid has been previously shown to counteract obesity via inhibiting adipogenesis, de novo lipogenesis, and pancreatic lipase activity, and/or enhancing catabolism of fatty acids, thus decreasing abdominal fat deposits and abdominal circumference." (PMID 33671116, 2021). "In 1991, Kiely J.S. used it to screen enzyme inhibitors, and, later, the literature reported that pancreatic lipase inhibitors in the middle have a preeminent behavior on the treatment of obesity and prevention of its complications." (PMID 34361800, 2021).
Obesity (continued). "OrlistatTM is the only pancreatic lipase inhibitor currently approved for long-term treatment of obesity." (PMID 33916292, 2021). "The inhibition of pancreatic lipase activity and the suppression of dietary lipid absorption are considered to be anti-obesity mechanisms of EGCG." (PMID 33022003, 2020). "Pancreatic lipase activity is most widely used to determine in vitro anti-obesity activity since it is one of the important enzymes in hydrolyzing triglyceride and thus absorbing lipids in the small intestine." (PMID 32824369, 2020). "Inhibition of human pancreatic lipase, a crucial enzyme in dietary fat digestion and absorption, is a potent therapeutic approach for obesity treatment." (PMID 33066044, 2020). "This study was carried out to develop a dietary supplement ingredient that improves convenience of use and has good safety and obesity effects by respectively mixing natural plants having α-amylase inhibitory and pancreatic lipase inhibitory effects." (PMID 33036193, 2020). "Meanwhile, FR and its isolated compounds were reported to possess anti-obesity characteristics via inhibition of pancreatic lipase." (PMID 32326102, 2020). "Other important anti-obesity mechanism of seaweeds is related with inhibition of lipases, especially pancreatic lipase, that is one of the main therapeutic targets of anti-obesity drugs and was recently demonstrated for various seaweeds species." (PMID 32102343, 2020). "Phenols act as anti-obesity agents through different mechanisms, including the inhibition of enzymes such as pancreatic lipase." (PMID 32664218, 2020). "Pancreatic lipase inhibitory activity has been widely used for the investigation of the potential efficacy of compounds as anti-obesity agents." (PMID 32664218, 2020). "Orlistat is one of the drugs used in obesity treatment whose action is based on the inhibition of pancreatic lipase activity." (PMID 32471271, 2020). "It has been clinically reported that a pancreatic lipase inhibitor, orlistat, prevented obesity and hyperlipidemia through the increment of fat excretion in the feces and the inhibition of pancreatic lipase." (PMID 33036193, 2020). "One of the best therapeutic strategies for obesity management is through the inhibition of pancreatic lipase (PL) enzyme." (PMID 33008398, 2020). "In the human body, fat is hydrolyzed by pancreatic lipase and then absorbed in the small intestine, therefore, pancreatic lipase inhibitors can be used to prevent/treat obesity." (PMID 32887336, 2020). "One of the most effective ways GT can contrast obesity is through the inhibition of enzymes such as pancreatic lipase, amylase, and glucosidase in the gastrointestinal (GI) tract." (PMID 32962190, 2020). "The inhibition of pancreatic lipase activity was one of the solutions to avoid obesity complication." (PMID 31240213, 2019). "Pancreatic lipase activity is therefore widely considered as one of the most important indicators for the determination of the anti-obesity potential of natural products." (PMID 30626104, 2019). "Studies have also shown that saponins inhibit pancreatic lipase activity and are considered to have anti-obesity and cholesterol-lowering properties." (PMID 31487939, 2019). "Inactivation of PL has been proven to have anti-obesity effects by forming a covalent bond with gastric and pancreatic lipase in the gut and stopping lipases turning dietary fat into absorbable monoglycerides and free fatty acids." (PMID 31538117, 2019). "Pancreatic lipase (PL) is an enzyme that plays an essential role in the digestion of dietary lipids and is a suitable target for an anti-obesity dietary supplement." (PMID 31792306, 2019). "Inhibition of dietary triglyceride absorption via pancreatic lipase inhibition likely represents a new approach for obesity treatment." (PMID 31057650, 2019). "The inhibition of pancreatic lipase activity is the most widely studied mechanism for the identification of potential anti-obesity agents." (PMID 31488210, 2019).